HIF1A (hypoxia inducible factor 1 subunit alpha)
Diseases named in the same sentence as HIF1A in open-access papers (continued):
Sharing a sentence is not in itself a finding about the gene and the disease.
breast cancer (continued). "In addition, clinical studies have shown that both HIF-1α and LOX are overexpressed in breast cancer patients, and this overexpression increases with disease progression and is associated with a high mortality rate." (PMID 33126606, 2020). "For HIF-1α-TWIST interaction, HIF-1α could bind directly to TWIST by HRE in the TWIST proximal promoter in hypopharyngeal and breast cancer cell lines." (PMID 32322559, 2020). "Moreover, a recent study has shown that exogenous supplementation of AKG prevented tumor growth and metastasis of breast cancer cells through stabilization of PHD2 and decreasing HIF-1α." (PMID 33321940, 2020). "Such a model is supported by the increased HIF1A signaling in patient blood-derived CTC lines with high growth potential in the brain, as well by the heterogeneity of freshly isolated single CTCs from women with metastatic breast cancer." (PMID 33298946, 2020). "The aims of this study were to evaluate the expression of HIF-1α and VEGF in feline mammary carcinomas and analyze their correlations with clinical and pathological factors, such as clinical stage, histologic grading, regional metastasis, and overall survival rate." (PMID 32375802, 2020). "Similarly, in breast cancer cells, miR-497 downregulates VEGF and HIF-1α levels, thus reducing tumor growth and angiogenesis, as demonstrated both in vitro and in vivo." (PMID 31757094, 2019). "Resveratrol downregulated HIF-1α expression occurs at the protein level, but not at the transcript level in human breast cancer cells (MCF-7 cells)." (PMID 30791624, 2019). "Overexpression of miR-181c in breast cancer cells blocked HIF-1α accumulation and diminished hypoxia-inducible levels of glycolysis enzymes, whereas the inhibition of miR-181c in NRF2-silenced cells restored HIF-1α accumulation." (PMID 31078780, 2019). "Furthermore, inhibition of HIF-1α hydroxylation and degradation via EV transmission of HIF-1α stabilising long noncoding RNA (HISLA) from TAMs has also been shown to enhance aerobic glycolysis and apoptotic resistance of breast cancer cells." (PMID 31835751, 2019). "Hypermethylation or hypomethylation of non-CpG sites within the HIF-1α promoter around the TSS have not previously been described in breast cancer." (PMID 30940798, 2019). "We previously demonstrated that, in resistant colon cancer, chronic lymphocytic leukemia, pleural malignant mesothelioma, non small cell lung cancer, and breast cancer, ERK1/2 phosphorylates and stabilizes the hypoxia-inducible factor-1α (HIF-1α), a strong inducer of Pgp." (PMID 31117237, 2019). "In a study on breast cancer cells, it was found that the transcription factor HIF-1α is responsible for this increase in EV production, since the release of EVs was blocked upon silencing of HIF-1α." (PMID 30783517, 2019). "Moreover, copper was reported to increase the ROS-mediated expression of VEGF, HiF-1α, and G-protein estrogen receptor (GPER) in HepG2 hepatocellular carcinoma cells and SkBr3 breast cancer cells via activation of the EGFR/ERK/c-Fos pathway." (PMID 31766246, 2019). "To avoid possible omission of methylated loci, we analyzed DNA methylation at non-CpGs (CpHs) in the first exon of the HIF-1α gene in various breast cancer cell lines." (PMID 30940798, 2019). "Conversely, tHIF-1α expression was barely detectable, whereas DNMT3a exhibited higher expression levels in ERα + breast cancer cell lines such as MCF-7 and T47D, suggesting that DNMT3a is most likely involved in methylation in the first exon of the HIF-1α gene in MCF-7 cells." (PMID 30940798, 2019). "HIF-1α may partially account for the metastatic, invasive, and chemoresistant particularities of TNBC compared to the other breast cancer subtypes." (PMID 31394796, 2019). "Another study revealed that in breast cancer cells, p16, a tumor suppressor gene, interacts and binds with HIF-1α, which in turn may alter HIF-1α’s capability to transactivate VEGF expression." (PMID 30871059, 2019).
breast cancer (continued). "Likewise, the GOBO database also shows that HIF-1α expression levels in basal-like and HER2 + subtypes are significantly higher other breast cancer subtypes." (PMID 30940798, 2019). "Similarly, HIF-1α is regulated by miR-21 in the CSC-like cells of breast cancer cells, with antagonism of the miRNA suppressing EMT, CSC-like qualities and HIF-1α." (PMID 31552162, 2019). "In control mice not exposed to HF diet in utero, VPA/hydralazine increased mammary tumor incidence and burden, and elevated expression of the unfolded protein response and autophagy genes, including HIF-1α, NFkB, PERK, and SQSTM1/p62." (PMID 31889127, 2019). "We showed that cardamonin treatment reduced HIF-1α expression in TNBC cell lines, and subsequently inhibited glycolysis and increased mitochondrial OXPHOS and ROS accumulation, finally induced cell apoptosis in breast cancer cells in vitro and in vivo." (PMID 31455352, 2019). "Tumor HIF-1α-positivity correlated to increased breast cancer mortality, and negative prognostic factors including low age at diagnosis and ER-negativity." (PMID 31821370, 2019). "Accordingly, it has been found that HIF1α stabilization through hypoxia and/or TGFβ upregulates the expression of the extracellular matrix modifying enzyme collagen prolyl-4-hydroxylase (P4HA) in breast cancer cells." (PMID 31069166, 2019). "Taken together, there is a possibility that in breast cancer, lack of vitamin C hinders the degradation of HIF-1α, which in turn promotes metastasis." (PMID 31817810, 2019). "It is therefore interesting to investigate whether Rac1 and HIF-1α work as downstream effectors of SOX2 and NEDD9 in hypoxic breast cancer cells." (PMID 31462898, 2019). "HIF-1α dependent BAX expression during hypoxia revealed that after certain extent of hypoxia induction, over expression of BAX conquers the effect of anti-apoptotic proteins and ultimately leads to apoptosis in breast cancer cells." (PMID 30876462, 2019). "Via DNA extraction and bisulfite sequencing, respectively, we found uniform hypermethylation at CpG and non-CpG sites within the promoter and first exon of the HIF-1α gene in luminal subtype breast cancer samples and hypomethylation in TNBC samples." (PMID 30940798, 2019). "Collectively, these data indicate that there exists hypermethylation at CpG and non-CpG sites within the first exon of the HIF-1α gene in human luminal subtype breast cancer samples as compared to TNBC samples." (PMID 30940798, 2019). "We recently found that the HIF-1α gene bears a canonical ER-binding element that responds to estrogen signaling, demonstrating a direct regulatory link between the ERα and HIF-1α pathways in breast cancer." (PMID 31152137, 2019). "Specifically, they showed that loss of E-cadherin and/or overexpression of its repressors, such as ZEB1, downregulates the expression of HIF-1α and CAIX, leading to a reduction of the extracellular acidification of inflammatory breast cancer cells, tumor growth, and metastasis formation." (PMID 31010154, 2019). "In breast cancer cells, the authors showed that WWOX knock down increases HIF1α in MCF7 cells." (PMID 30619734, 2018). "For instance, EGFR and Her2 signaling have been shown to increase the rate of HIF-1α synthesis and the subsequent expression of survivin and VEGF in breast cancer cells, through the involvement of the PI3k/AKT pathway and the downstream kinase FRAP (FKBP-rapamycin-associated protein)." (PMID 29996493, 2018). "The loss of SINHCAF resulted in significant increases in HIF-2α with little or no change to HIF-1α protein following exposure to hypoxia in breast cancer cells (MDA-MB-231) and two colorectal (SW480, DLD-1) cell lines." (PMID 29784889, 2018). "HIF-1α knockdown or TGF-β blockade has also been shown to reduce bone metastasis and increase survival in mice implanted orthotopically with human MDA-MB-231 breast cancer cells." (PMID 29098360, 2018).
breast cancer (continued). "It has been shown that presence of HIF-1α is a negative prognostic factor for breast cancer both in lymph node positive and negative tumors." (PMID 29552303, 2018). "The aim of this review is to outline the most significant findings supporting the proposal that a signaling network between HIF-1α, GPER and Notch may integrate tumor microenvironmental cues to induce robust EMT in breast cancer cells." (PMID 29996493, 2018). "PLOD2 is induced by hypoxia-inducible factor-1α (HIF-1α) under hypoxia condition, which in turn enhance hypoxia-induced Epithelial-Mesenchymal Transition (EMT) phenotypes in glioma cells and breast cancer cells." (PMID 30003082, 2018). "In breast cancer cells, prolonged treatment with the metabolic intermediate dimethyl α-ketoglutarate (DKG) leads to accumulation of succinate and fumarate, which induces hypoxia-inducible factor 1α (HIF-1α) to promote both glycolysis and OXPHOS to enable the plasticity of breast cancer cells." (PMID 29996946, 2018). "Moreover, HIF-1α induces expression of stemness factors, including Oct-4 and NANOG, and cancer cell plasticity observed in breast cancer is also dependent on HIF-1α." (PMID 29996946, 2018). "Indeed, GPER was shown to cooperate with HIF-1α for the expression of invasive markers, including CTGF, VEGF and IL-6 in both breast cancer cells and CAFs exposed to low oxygen." (PMID 29996493, 2018). "Importantly, in endocrine therapy-resistant breast cancer cells, the regulation of KDM4B by HIF-1α and ERα is intact and KDM4B is still required for G2/M phase progression." (PMID 29342868, 2018). "A recent study from Semenza’s group showed that HIF-1α activated transcription of CD47 in mesenchymal triple-negative primary breast cancer cells (SUM159) and promoted the breast cancer stem cell phenotype, which further protected cancer cells from phagocytosis by bone marrow-derived macrophages." (PMID 30061885, 2018). "Similarly, 7-chloro-fascaplysin inhibited cell survival through interference with the PI3K/Akt/mTOR pathway, which in turn modulates HIF-1α, eNOS and MMP-2/9 in a breast cancer cell line." (PMID 30322180, 2018). "Because, among the molecules up-regulated by hypoxia through the activity of HIF-1α, the cell surface protein carbonic anhydrase IX (CAIX) is one of the more specific for non-invasive breast cancer cells, this protein was evaluated in MCF10DCIS cells cultured under hypoxia." (PMID 30497437, 2018). "An equivalent robust upregulation of HIF2α, but not of HIF1α, was observed in primary breast cancer cells." (PMID 29993038, 2018). "Moreover, results from a randomized trial enrolling 211 breast cancer patients undergoing neoadjuvant epirubicin therapy showed upregulated expression of PHD1, PHD2 and PHD3, together with HIF-1α, VEGF and carbonic anhydrase IX (CAIX)." (PMID 29996493, 2018). "In concordance with our previous results, high ∆Np73 levels did not correlate with any significant changes in VHL or HIF-1α mRNA levels in the breast cancer patients." (PMID 29628507, 2018). "As pivotal players of HIF-1α regulation, PHDs and VHL are frequently deregulated in breast cancer and may serve as useful prognostic markers." (PMID 29996493, 2018). "Cancer cell-specific PHD2 haplodeficiency in the MMTV-PyMT breast cancer model led to increased HIF-1α and HIF-2α stabilization, but that did not have an effect on tumor growth or directly on the cancer cells’ invasive behavior." (PMID 29896451, 2018). "Extending these findings, the HIF-1α-mediated release of TGF-β in hypoxic breast tumor microenvironment triggers Mesenchymal Stem Cells (MSCs) activation, thereby promoting growth, motility and invasive effects in breast cancer cells." (PMID 29996493, 2018). "Of note, HIF-1α expression in normoxic conditions was shown to mediate certain detrimental effects dependent on HER2 action and involved in the resistance to aromatase inhibitors in breast cancer cells." (PMID 29996493, 2018).
breast cancer (continued). "In addition, in a transgenic mouse model of breast carcinoma development (MMTV-PyMT), Doedens and colleagues demonstrated that targeted deletion of HIF-1α in macrophages leads to reduced breast tumor growth." (PMID 29434587, 2018). "It has been recently reported that MTA1 enhances the transcriptional activity of HIF-1α in human breast cancer cells, but the relationship between MTA1 and HIF-1α in HCC is unknown." (PMID 28589145, 2017). "Additionally, it has been found that EMT program promotion, by the increased HIF-1α and TGF-β signaling, induced over-expression of CXCR4 and VEGF in breast cancer cells collaborated in their diffusion and secondary bone involvement." (PMID 29099748, 2017). "Furthermore, EGCG significantly inhibited the activation of HIF-1α and VEGF expression in cultured breast cancer cells in vitro." (PMID 29271940, 2017). "Recently, HIF1A has been shown to induce VTCN1 in multiple myeloma, cervical, and breast cancer cell lines, which may be a part of the mechanism by which VTCN1 is regulated in IMA." (PMID 28255028, 2017). "In addition, in breast cancer cells and CAFs as well as in a mouse model of breast cancer, estrogenic GPER signaling has been shown to trigger HIF-1α/VEGF pathway leading to angiogenesis and tumor growth." (PMID 29212519, 2017). "Moreover, miR-199b also functions as a tumor suppressor in medulloblastoma, hepatocellular carcinoma and breast cancers by affecting targets such as HEIS1, HIF1α or HER2." (PMID 27517624, 2017). "SHARP1 has been reported to be a crucial regulator in the proteasomal degradation of HIF-1α for breast cancer progression without pVHL (von Hippel-Lindau tumor suppressor), hypoxia, and the ubiquitination mode." (PMID 28903320, 2017). "Many studies also indicate that the expressions of HIF-1a and CA IX are independent of tumor size in the breast cancer." (PMID 29206859, 2017). "Specifically, this may occur through the release by both types of cells of growth factors and cytokines, such as SDF-1, TGF-β1 and BMPs, and over-expression of HIF-1α, NF-κB, vascular cell adhesion molecule-1 (VCAM-1) and Notch in breast cancer cells." (PMID 29099748, 2017). "Similarly, in breast cancer cells and Hep3B hepatoma cells, complexes constituted by STAT3, CBP/p300, RNA polymerase II (Pol II), and HIF-1α are reported to regulate HIF-1α target genes including VEGF." (PMID 28978186, 2017). "In addition to SET, miR-199b has been reported to regulate other important targets such as HEIS1, HIF1α or HER2 in medulloblastoma, hepatocellular carcinoma and breast cancers." (PMID 27517624, 2017). "Interestingly, GPER is a direct HIF1-α target and is up-regulated following HIF stabilization in breast cancer cells." (PMID 29137421, 2017). "Taken together, these results indicate that Parkin plays a critical role in suppressing breast cancer metastasis in vivo through ubiquitination and negative regulation of HIF-1α." (PMID 29180628, 2017). "Hypoxic stress, which induces the accumulation and nuclear translocation of ARNT and HIF1A, has been shown to suppress RNAPIII recruitment and tDNA expression in cardiomyocytes and increase levels of tRNA-derived fragments in breast cancer and mammary epithelial cells." (PMID 28931413, 2017). "In contrast, HIF1a downregulation by VHL over-expression, anti-miR-101 oligo administration or 2-MeOE2 treatment rescued cells from miR-101-mediated apoptosis and cell cycle arrest in breast cancer cells." (PMID 26841847, 2016). "In our study, HIF-1α and PGC-1α were measured in all breast cancer patients." (PMID 27780920, 2016). "The knockdown of either HIF-1α, P4HA1, or P4HA2 decreases tumor fibrosis and P4HA1 or P4HA2 knockdown completely abrogates the spontaneous metastasis of mammary fat pad-implanted human breast cancer cells to the lungs and lymph nodes of immunodeficient mice." (PMID 27706047, 2016). "High levels of HIF-1α and PGC-1α were both related to more aggressive types of breast cancer." (PMID 27780920, 2016).
breast cancer (continued). "Finally, in breast cancer mRNA samples, a positive correlation of MCU expression with HIF‐1α signaling route is present." (PMID 27138568, 2016). "Moreover, HIF‐1α upregulates lysyl‐oxidase (LOX) which, in breast cancers, controls migration and invasion." (PMID 27138568, 2016). "For example, breast cancers arising in conditional-knockout mice lacking HIF-1α expression in mammary epithelial cells showed significantly reduced lung metastasis compared to breast cancers arising in wild type mice." (PMID 27706047, 2016). "Secondly, based on the fact that HIF-1α and PGC-1α are sharing several cellular pathways, we investigated whether PGC-1α is also showing prognostic features in breast cancer." (PMID 27780920, 2016). "Hypoxia or overexpression of HIF-1α induces a metastastic phenotype in otherwise non-metastatic breast cancer cells via a TWIST-dependent mechanism in vivo; TWIST short-interfering RNA (siRNA) can reverse this effect." (PMID 27706047, 2016). "Taken together, these data suggest that HIF2α, but not HIF1α, mediates hypoxia-induced breast cancer growth and that EFEMP1 promotes BCSC renewal and tumor metastasis as a downstream effector of hypoxia-induced HIF2α during breast tumorigenesis." (PMID 27270657, 2016). "We addressed the critical question whether there is a reliability of HIF-1α and PGC-1α to be used as markers to predict prognosis in breast cancer patients." (PMID 27780920, 2016). "We also found that EMMPRIN could down-regulate miR-106a and miR-106b expression in breast cancer cells, which led to activating STAT3 and enhancing HIF-1α expression." (PMID 27325313, 2016). "Taken together, we found that HIF-1α and PGC-1α overexpression has prognostic significance in breast cancer patients and may present potential opportunities in breast cancer therapy." (PMID 27780920, 2016). "In a study of 83 breast cancer patients with neither lymph node metastases nor overt distant metastases, high HIF-1α protein levels in primary tumor tissue correlated with the presence of cancer cells in bone marrow aspirates." (PMID 27706047, 2016). "Most strikingly, in our multivariate analysis, which was also employed to evaluate the clinical impact of HIF-1α/ PGC-1α plasma level on prognosis, PGC-1α plasma level was an independent prognostic factor for disease free survival in breast cancer patients (HR=1.582, 95.0% CI 0.951~2.633, P < 0.1)." (PMID 27780920, 2016). "This suggests that HIF-1α and PGC-1α may stimulate tumor development and metastasis, and to have power to predict the prognosis in breast cancer patients." (PMID 27780920, 2016). "Therefore, in our study, we aimed to investigate the role of HIF-1α, as well as PGC-1α in breast cancer tumorigenesis, growth and metastasis." (PMID 27780920, 2016). "We conducted a prospective, long-term follow up study to determine whether HIF-1α and PGC-1α can be implemented as predictive biomarker in breast cancer." (PMID 27780920, 2016). "Since DEK promotes VEGF secretion in breast cancer cells in HIF-1α-dependent and -independent manners, we tested the effect of the conditioned medium derived from knockdown DEK or DEK and HIF-1α knockdown stable breast cancer cell lines on HUVEC proliferation and migration." (PMID 26988756, 2016). "Our immunohistochemical studies show that HIF-1α and TAZ are remarkably expressed in primary ductal breast carcinoma throughout the neoplastic cells, while in bone metastases their signals are elevated and localized in nuclei, consistent with the role of TAZ as a co-factor of HIF-1." (PMID 27187355, 2016). "Glycolytic genes not known to be dependent upon HIF-1α induction demonstrated similar expression between breast cancer specimens and benign tissues." (PMID 26316122, 2015). "Thus, bidirectional functional interactions between HIF-1α and TAZ synergistically drive the expression of downstream target genes in hypoxic breast cancer cells." (PMID 26059435, 2015).